S1PR1 (sphingosine-1-phosphate receptor 1)
Diseases named in the same sentence as S1PR1 in open-access papers (continued):
Sharing a sentence is not in itself a finding about the gene and the disease.
heart diseases (3 papers, 2020 to 2025). "As mentioned, maintenance of S1P/S1PR signalling plays an important and protective role against cardiovascular endothelial dysfunction; however, overstimulation of the inflammatory response by S1P/S1PR1 is also a major factor in heart disease and heart failure." (PMID 33003377, 2020). "Blocking the S1P/S1PR1-mediated inflammatory response by FTY720 administration has been shown to exhibit positive effects against heart disease, and, as observed in ischaemia and hypoxic injury mouse models, it has been proven to be protective against acute and chronic myocardial injury." (PMID 33003377, 2020). "Notably, S1PR1 is predominantly expressed in cardiomyocytes, and prior studies have shown that cardiomyocyte-expressing S1PR1 influences heart development and the pathological processes of heart diseases 16-18." (PMID 39816679, 2025).
immune diseases (3 papers, 2018 to 2023). "It is suggested that there are similar molecular mechanisms by which S1PR1 regulates downstream target genes in T cells in other immune diseases." (PMID 37858140, 2023).
retinopathy (3 papers, 2023 to 2025). "Both S1P bound to ApoM‐Fc and a small molecule Gi‐biased S1PR1 agonist suppressed pathological neovascularization in oxygen‐induced retinopathy." (PMID 36975378, 2023). "Here, we show in a mouse model of oxygen‐induced retinopathy (OIR) that endothelial overexpression of S1pr1 suppresses while endothelial knockout of S1pr1 worsens neovascular tuft formation." (PMID 36912000, 2023). "Circulating HDL‐S1P activation of endothelial S1PR1 may be a key protective mechanism to guard against neovascular retinopathies that occur not only in premature infants but also in diabetic patients and aging people." (PMID 36912000, 2023).
neurological diseases (2 papers, 2016 to 2025). "In contrast, several modulators of S1PR1 are already approved for the clinical treatment of immune-mediated and neurological diseases, with several additional compounds in various stages of clinical development." (PMID 41511294, 2025).
infectious disease (1 paper, 2021). A disorder directly resulting from the presence and activity of a microbial, viral, or parasitic agent in humans. "In fact, accumulated evidence suggests that S1PR1 activation and signaling are impaired during infectious disease." (PMID 34934406, 2021). "It was reported that S1PR1 plays an important role in the immune response to infectious diseases by regulating recruitment and trafficking of innate immune cells, macrophage polarization, and dendritic cell functions." (PMID 34934406, 2021). "PET with S1PR1-specific radiotracer [18F]TZ4877 could provide a noninvasive tool for detecting the early S1PR1 immune response to infectious diseases." (PMID 34934406, 2021).
psychiatric diseases (1 paper, 2023). "For instance, S1PR1 stimulation in the context of psychiatric diseases can be seen as deleterious for increasing inflammation but beneficial for promoting barrier integrity." (PMID 37628815, 2023).
skin disorder (1 paper, 2020). Any deviation from the normal structure or function of the skin or subcutaneous tissue that is manifested by a characteristic set of symptoms and signs. "S1PR1 mRNA expression level in SLE patients with skin disorder was significantly higher than SLE patients without skin involvement, while it was lower in the SLE patients with central nervous system (CNS) involvement compared with SLE patients without this manifestation." (PMID 33574820, 2020).
vasculopathies (1 paper, 2020). "Such mechanistic studies will help to determine the utility of S1PR1 modulators in treating lymphatic-mediated vasculopathies." (PMID 32091396, 2020).
S1PR1 also shares sentences with these, for which no sentence is quoted: colon cancer (8 papers); relapsing-remitting multiple sclerosis (8); leukemia (3); medulloblastoma (3); Myocardial fibrosis (3); neurodegenerative disease (3); proliferative diabetic retinopathy (3); secondary progressive multiple sclerosis (3); vitiligo (3); acute kidney injury (2); adenocarcinoma (2); anemia (2); clear cell renal cell carcinoma (2); Crohn disease (2); head and neck squamous cell carcinoma (2); hemangiosarcoma (2); kidney damage (2); lupus nephritis (2); Lymphadenopathy (2); mantle cell lymphoma (2); neuropathy (2); non-small cell lung carcinoma (2); peripheral neuropathy (2); pneumonia (2); renal carcinoma (2); renal cell carcinoma (2); respiratory diseases (2); Sjögren’s syndrome (2); subarachnoid hemorrhage (2); type 1 diabetes (2).
A further 93 diseases each share a sentence with S1PR1 in 1 paper.